TNF (tumor necrosis factor)
Diseases named in the same sentence as TNF in open-access papers (continued):
Sharing a sentence is not in itself a finding about the gene and the disease.
COVID-19 (continued). "In patients with severe COVID-19, high levels of circulating IL-6, IL-1β, INFγ, and TNF-α have been reported, together with an unbalanced white cell formula, consisting of high neutrophils and decreased CD4+ and CD8+ T cells." (PMID 35140702, 2021). "One preliminary study compared TNF-α, IL-6 and IL-8 levels in critically ill COVID-19 vs. non-COVID-19 patients." (PMID 34945111, 2021). "Increased concentrations of inflammatory cytokines (IL-6, granulocyte-macrophage colony stimulating factor (GM-CSF) and tumor necrosis factor-a (TNF-a) are reported in persons with COVID-19." (PMID 34002026, 2021). "Significantly higher concentration of TNF-α (p = 0.001), IL-1β (p = 0.001), IL-6 (p = 0.001), IL-12 (p = 0.001), IL-23 (p = 0.043), and IL-33 (p = 0.001) have been found in the sera of COVID-19 patients with severe disease." (PMID 34917631, 2021). "Cytokine storm mediated by proinflammatory cytokines such as interleukin-6 (IL-6) and tumor necrosis factor-alpha (TNF-α) is probably the culprit for severe COVID-19." (PMID 34178527, 2021). "IL-1 and TNF were strong inducers of hyaluronan-synthase-2, an important factor for the pathological changes of ARDS and a potential cause of COVID-19 fatality." (PMID 34766001, 2021). "Increasing evidence suggests that cytokines such as IL-6, IL-1β receptor, IFN-γ, and TNF-α play a key role in the pathogenesis of COVID-19." (PMID 33995341, 2021). "Based on these findings, after the outbreak of the COVID-19, the use of TNF-α inhibition to treat this disease was proposed." (PMID 34938746, 2021). "Serum levels of IL-6 and TNF-alpha were higher in COVID-19 children than in children with other infectious diseases, but those levels did not correlate with disease severity." (PMID 34578450, 2021). "In line with the herein results, patients with COVID-19 treated with MSCs showed lower levels of TNFα, whereas they showed lower levels of IL-6 and higher levels of IL-10 in plasma/serum samples." (PMID 33634100, 2020). "The possible benefit of TNF-blockers was also observed in a cohort from the US and underscores the role of the overabundance of TNF in critically ill COVID-19 patients." (PMID 33154972, 2020). "This adds an additional challenge to the proper interpretation of the safety of anti-TNF use during an active episode of COVID-19 and its potential effect on complications’ occurrence." (PMID 33426360, 2020). "Inflammation involving the cytokine TNF alpha can cause ENaC and CFTR and epi‐ and endothelial barrier dysfunction and is a dominant feature of COVID-19 induced ARDS." (PMID 32922301, 2020). "The underlying pathophysiology of COVID-19 involves a maladaptive immune response to SARS-CoV-2 infection with increased levels of IL-6, IL-10, IL-2 and TNFα produced by macrophages, and fewer CD4+ and CD8+ T cells, but no significant changes in B-cell counts." (PMID 32399655, 2020). "Elevated serum concentrations of IL-6, tumor necrosis factor–α (TNF-α), and other inflammatory cytokines have been described in adults with COVID-19, particularly those who progress to ARDS." (PMID 32958614, 2020). "Elevated TNF-α levels seen in a variety of clinical conditions including COVID-19, drives cardiomyocytes to apoptosis." (PMID 33363221, 2020). "Results are explorative but indicate that DPSCs can down-regulate the production of cytokines by activated PBMCs, e.g., TNFα, IFNγ, IL-10, and IL-17A, which are up-regulated in COVID-19 patients." (PMID 33634100, 2020). "Several cytokines and chemokines, including TNF, were upregulated, consistent with observations in COVID-19 patients." (PMID 33228225, 2020). "An increase in systemic interleukins, chemokines, and tumor necrosis factor-α (TNF-α) has been observed during the rapid progression phase of COVID-19." (PMID 32521760, 2020). "Some results, like the role and category of comorbidities, are in line with the general population experiencing COVID-19, others, like the protective effect of TNF-blockers were unexpected." (PMID 33154972, 2020).
COVID-19 (continued). "Conversely, an increased TNF/IL-1β-driven inflammatory response was observed in severe COVID-19 patients as compared to severe influenza, and to mild COVID-19 patients." (PMID 33129318, 2020). "There is sufficient evidence to support clinical trials of anti TNF-α therapy in patients with COVID-19." (PMID 33276686, 2020). "Impaired cellular functionality in CD4+ and CD8+ T cells has been observed in severe COVID-19 cases along with generally lower interferon γ (IFNγ) and tumor necrosis factor α (TNF-α) production." (PMID 33362779, 2020). "In the current study, we demonstrated that severe COVID-19 is characterized by TNF/IL-1β-inflammatory features combined with the IFN-I response." (PMID 32651212, 2020). "Our study showed that TNF-α is a potent cytokine related to pathological inflammation in tissues—similar to IL-6—in patients with COVID-19." (PMID 33424804, 2020). "Higher levels of several inflammatory cytokines including TNF-α, IL-6, and IL-1 and inflammatory chemokines such as CCL2, CCL3, and CXCL10 are associated with disease severity and death in COVID-19 patients." (PMID 33138195, 2020). "In one of the very first reports of the clinical course of COVID-19 patients, as early as March 2020, serum increase in interleukin (IL)-2, IL-7, GMCSF, IP-10, MCP 1, MIP1-α, and TNF-α was associated to disease severity." (PMID 33019628, 2020). "PBMCs were also stimulated overnight with LPS to activate monocytes, and the numbers of TNF-α–producing cells were determined for COVID-19, septic, and CINS patients." (PMID 32687484, 2020). "Anti-TNF treatment has even been suggested for the treatment of COVID-19, attenuating disease progression and leading to milder outcomes by suppressing systemic auto-inflammatory responses." (PMID 32882823, 2020). "In Castleman disease, IL-6 is elevated in conjunction with TNFα, IL-1β and IL-10 as in severe COVID-19; however, vascular manifestations are unusual in this condition." (PMID 32629875, 2020). "Elevated levels of cytokines such as IL1-β, IL-7, IL-8, IL-9, IL-10, granulocyte-macrophage colony-stimulating factor (GMCSF), IFN-γ, monocyte chemoattractant protein (MCP1), and tumor necrosis factor-α (TNFα) has been reported in COVID-19." (PMID 33224529, 2020). "In this context, we herein demonstrate that mononuclear cells, which were isolated from subjects following severe COVID-19, had higher mRNA expression levels of cytokines such as TNF and IL10, as compared to individuals with milder disease." (PMID 33087116, 2020). "Although experimental evidence is needed, these observations suggest a possible role of lymphocyte autophagy in TNF-mediated inflammatory excess in patients with COVID-19." (PMID 33424586, 2020). "In COVID-19 patients, a profile of cytokines, such as IL-2, IL-6, IL-7, INF-γ, and TNF-α, is associated with disease severity and mortality of patients." (PMID 33679608, 2020). "It is now appreciated that COVID-19 afflicted individuals with major respiratory symptoms have pathologically elevated levels of pro-inflammatory cytokines including IL-6, IL-8 and TNF-α." (PMID 32704455, 2020). "A detailed analysis of 1,484 patients with COVID-19 showed that TNF and IL-6 levels, independently correlated with disease outcome." (PMID 33574819, 2020). "A literature search was performed using the databases PubMed, EMBASE, and Web of Science to collect the levels of cytokine including IL-1β, IL-6, IL-18, TNF-α, IL-10, and ferritin in severe COVID-19 patients." (PMID 33552062, 2020). "Patients suffering from severe coronavirus disease 2019 (COVID-19) show highly elevated levels of Gal-3, TNFα, IL-1β, and IL-6, as compared to those with moderate disease (De Biasiet al., 2020;Wanget al., 2020a)." (PMID 33082935, 2020). "In the present study, IL-2R, IL-6, TNF-α, and hs-CRP were significantly higher than the normal range and higher in the AKI group, and PCT more than 0.1 ng/mL was found to be associated with COVID-19-related AKI." (PMID 32850917, 2020).
COVID-19 (continued). "Compared with healthy volunteers, stimulated PBMCs from COVID-19 patients had half as many TNF-α–producing cells (healthy, 177.5 ± 27)." (PMID 32687484, 2020). "It has been demonstrated that increased levels of pro-inflammatory cytokines, including interleukin 1β, interleukin 6 (IL-6), and tumor necrosis factor alpha (TNFα), in patients with COVID-19 can induce upregulation of procoagulants." (PMID 33118741, 2020). "The transplanted MSCs significantly elevated IL-10 and reduced TNF-α concentrations in seven MSC transplanted patients with COVID-19-pneumonia compared to the three patients in the placebo control group receiving standard care." (PMID 33363221, 2020). "SARS-CoV-2 spike protein can induce IL-8, IL-6 and TNF-α secretion in monocyte-derived macrophages (MDMs) and specifically primes COVID-19 patient-derived MDMs for IL-1β production in vitro." (PMID 34192268, 2020). "Reminiscent of the cytokine profiles of COVID-19 patients with severe disease, acute KD is characterized by high levels of IL-6, TNF-α, and TGF-β." (PMID 33244300, 2020). "Results showed that COVID-19 patients have higher serum level of cytokines (TNF-α, IFN-γ, IL-2, IL-4, IL-6 and IL-10) and CRP than control individuals." (PMID 32475230, 2020). "COVID-19 patients exhibit abnormal immune responses related to high levels of proinflammatory cytokines, including TNFα and IL-6." (PMID 32708495, 2020). "Our case highlights the course of a patient, treated with a TNF-alpha inhibitor in combination with an immunomodulator, who developed COVID-19." (PMID 32824122, 2020). "At the same time, T cell counts recovered was related to the concentration of cytokines in plasma likes IL-6, IL-10, and TNF-α, which was decreased in the disease resolution stage of COVID-19 patients." (PMID 33261583, 2020). "We next assessed how monocyte alterations varied over the patients’ hospital stay and noted that patients with mild COVID-19 had consistently higher TNF-α and COX-2 expression in LPS-activated monocytes compared to patients with severe disease." (PMID 32943497, 2020). "We first compared the levels of IFN-γ, TNF-α, IL-2, IL-4, IL-6 and IL-10 in serum samples from control group and COVID-19 patients." (PMID 32475230, 2020). "Together with PI3Kδ inhibitor Idelalisib, Ebastine treatment in COVID-19 also appears to be an excellent inhibitory drug approach to T-cell pro-inflammatory cytokines IL-6 and TNF-α as demonstrated in allergic diseases." (PMID 32973818, 2020). "Similar findings were reported in a cohort of over 1,5000 patients, where serum IL-6 and TNF-α were found to be independent predictors of disease severity and mortality in COVID-19 (Del Valleet al., 2020)." (PMID 33082935, 2020). "Of the 10 patients developing COVID-19 in course of b/tsDMARD treatment, 6 were receiving a TNF antagonist, 2 a JAK inhibitor, 1 abatacept, and 1 secukinumab." (PMID 33380344, 2020). "Anti-malarial drugs hydroxychloroquine and chloroquine that are know to decrease Th17-related cytokines; IL-6, IL-17, IL-22, TNFα and IL-1β have been evaluated for efficacy in COVID-19 treatment in several clinical trials." (PMID 33708109, 2020). "Further promising and potentially effective therapies for COVID-19 are the anti-TNF antibodies infliximab and adalimumab, which have also shown a good safety profile." (PMID 32521760, 2020). "TNF-α was significantly increased in the olfactory epithelium of the COVID-19 group compared to the control group." (PMID 33013637, 2020). "CSS mentioned earlier does not seem to appear after quinine administration in COVID-19 since the available data show that the release of TNF-α, the most important cytokine in determining the severity of COVID-19 symptoms, is inhibited by quinine." (PMID 33101440, 2020). "In COVID-19, TNF-α has been a prominent feature of patient deterioration, increasing in ICU patients in comparison to non-ICU." (PMID 32961074, 2020).
COVID-19 (continued). "Severe hospitalized COVID-19 patients overexpressed pro-inflammatory cytokines (i.e., IL-1 beta, IL-2, IL-6, IL-17, TNFα)." (PMID 33019628, 2020). "TCM and its preparations can achieve an antipyretic effect by inhibiting 1L-1, IL-6, TNF-α, and other pyrogenic cytokines, and also can indirectly achieve the effect of initial treatment of COVID-19 by inhibiting the cytokine storm." (PMID 33013395, 2020). "Across the 23 evaluated observational studies, the association between the levels of inflammatory markers and the severity of COVID-19 and the levels of CRP, TNF-, and IL-6 was significantly high in the group with severe COVID-19 compared to the mild group." (PMID 33244370, 2020). "Our results also demonstrated that severe COVID-19 patients had higher concentrations of IL-6, IL-8, IL-2,TNF-α, and IFN-γ in the serum than mild case patients, which suggested that the magnitude of cytokine storm was associated with the disease severity." (PMID 32484453, 2020). "The common point between COVID-19 and allergic diseases makes Ebastine a potential therapeutic choice and inhibiting the release of both TNF-α and granulocyte-macrophage colony-stimulating factor (GM-CSF)." (PMID 32973818, 2020). "Elevated levels of pro-inflammatory cytokines, interleukin-1 (IL1β), interleukin-6 (IL6), and tumor necrosis factor-α (TNFα) in moderate to severe COVID-19 cases contribute to the hyperinflammatory response." (PMID 33490110, 2020). "Obese patients develop severe COVID-19 sequelae, due to the high concentrations of TNF-α, MCP-1 and IL-6 produced in the meantime by visceral and subcutaneous adipose tissue and by innate immunity." (PMID 33160363, 2020). "TNF-α and IL-6 are important inflammatory cytokines, and we found that the levels of TNF-α and IL-6 in the plasma of patients with COVID-19 were significantly increased and positively correlated with the severity of the disease." (PMID 32976531, 2020). "Acute inflammation can increase the cytokine load such interleukins (IL-2, IL-7), tumor necrosis factors (TNF) which contribute to cytokine storm seen in COVID-19." (PMID 33195352, 2020). "COVID-19 courses range from mild symptoms up to multiple organ failure and death, triggered by excessively high serum cytokine levels (IL 1β, IL 6, TNF α, IL 8)." (PMID 33292846, 2020). "TNF-α is another pro-inflammatory cytokine implicated in the pathophysiology of CRS and ARDS in COVID-19." (PMID 33244300, 2020). "In conclusion, several cytokine-blockers (anti-IL-6, anti-IL-1, anti-TNF-α etc.)are currently under investigation for COVID-19 patients that are already in use or currently tested for the treatment of irAE." (PMID 33207589, 2020). "CDCs target multiple cytokine pathways (e.g., TNFα, IFN-γ, IL-1β, IL-6) that are associated with disease progression and poor outcomes in COVID-19." (PMID 32399655, 2020). "COVID-19 patients have high levels of circulating interleukin 2 receptor (IL-2R), IL-6, IL-10 and tumor necrosis factor α (TNFα)." (PMID 33365277, 2020). "A subset of COVID-19 patients had LPS-stimulated TNF-α production that was comparable to that occurring in other critically ill patients, while a large number of COVID-19 patients had reduced production." (PMID 32687484, 2020). "This phenomenon is also the main reason why although the number of CD4+ Th cells in the peripheral blood significantly decreased, the plasma levels of TNF-α and IL-6 significantly increased in patients with COVID-19." (PMID 32976531, 2020). "Based on this analysis of the primary COVID-19 data, elevated levels of CRP, TNF-α, and IL-6 were found to be associated with increased odds of the severe form of COVID-19 that can result in liver damage in these cases." (PMID 33244370, 2020). "NK cells showed lower percentages of CD107a, IFN-γ, IL-2, TNF-α and granzyme B than those in healthy donors in COVID-19 patients." (PMID 33371901, 2020).
COVID-19 (continued). "In patients with moderate COVID-19 the concentrations of IL-10, IL-6, and TNFα are within normal limits, and in the most severe patients they are very high." (PMID 32574327, 2020). "Production of inflammatory cytokines such as interleukin (IL)-1β and tumor necrosis factor (TNF)-α by SREBP-2 or NF-κB were also increased as the severity of COVID-19 increases." (PMID 32883951, 2020). "The levels of TNF-α and IL-6 in the peripheral blood were significantly increased in COVID-19 patients, the degree of this elevation was significantly correlated with the severity of disease." (PMID 32976531, 2020). "In a mouse model of ARDS, which is the main cause of death in COVID-19 patients, CD26 inhibition by sitagliptin alleviated histological findings of lung injury by inhibiting the expression of IL-1β, TNF-α, and IL-6." (PMID 33269102, 2020). "Daclatasvir was also shown to reduce SARS-CoV-2-induced enhancement of TNF-α and IL-6, key contributors to the cytokine storm, observed in some COVID-19 patients." (PMID 33024223, 2020). "In patients with COVID-19, the high serum levels of IL-6 and TNF-α are negatively correlated to T cells; contrariwise, it has been demonstrated that T cell levels were restored by reducing IL-6 and TNF-α concentrations." (PMID 32354030, 2020). "Our previous preliminary study of 21 patients with COVID-19 exhibited that levels of sIL-2R, IL-10, TNF-α, hsCRP, Fer, and LDH were higher in the severe group than in the moderate group." (PMID 32854750, 2020). "In chronic stages of COVID-19, increased concentrations of proinflammatory cytokines, such as tumor necrosis factor-α (TNF-α) and interleukins (IL), including IL-1 and IL-6 have been reported." (PMID 33324223, 2020). "Levels of (TNFα) for COVID-19 patients were lower than for septic shock patients but higher than for OHCA or trauma patients." (PMID 33142828, 2020). "This study suggests that severity of COVID-19 was characterized by increased TNF-α and IL-6 production." (PMID 32929061, 2020). "Since TNF is an inflammatory cytokine, whose levels are elevated in COVID-19, it is being tested for management of pulmonary complications in COVID-19 patients in a phase 2 clinical trial." (PMID 32784499, 2020). "The expression of IL-6, which plays an important role in the pathogenesis of COVID-19, is increased by TNF." (PMID 33329059, 2020). "Anti-IL-6, IL-1RA and anti-TNF-α agents are already being investigated for COVID-19 treatment and are relevant to neutrophils, which express the requisite cytokine receptors." (PMID 32943497, 2020). "Compared with patients with mild COVID-19, those with severe COVID-19 had significantly higher levels of TNF-α and NT-proBNP, and lower levels of CD4 T cells and albumin globulin." (PMID 33232275, 2020). "We noted that severe patients of COVID-19 had high amounts of inflammatory indicators (Ferritin and TNFα) in severe patients than mild ones, suggesting that the cytokine storm was associated with disease severity." (PMID 32393351, 2020). "In this regard, metal fume fever has been shown to produce fever, fatigue, muscle ache, cough, dyspnea, and an increase of several cytokines including IL-1β, IL-6, IL-8 and TNF-α, symptoms and cytokines that have already been described for COVID-19 patients." (PMID 32708755, 2020). "These cells represent a potentially underappreciated source of both IFNγ and proinflammatory cytokines, such as TNFα, and contributors of disease progression in COVID-19." (PMID 32431755, 2020). "Elevated plasma concentration of inflammatory mediators was observed in patients with COVID-19, including IL-6, IL-10, TNF-α, and other inflammatory cytokines, as well as ferritin and C-reactive protein." (PMID 33552062, 2020). "The significant increase in the levels of TNF-α and IL-6 in the plasma of patients with COVID-19 is related to many kinds of inflammatory immune cells that secrete inflammatory factors." (PMID 32976531, 2020).